GDF15 (growth differentiation factor 15)
Diseases named in the same sentence as GDF15 in open-access papers (continued):
Sharing a sentence is not in itself a finding about the gene and the disease.
chronic lung disease (4 papers, 2020 to 2025). According to the definitions of the American and British Thoracic Societies, including pulmonary functional tests, X-rays, and CT scans for items such as fibrosis, bronchiectasis, bullae, emphysema, nodular or lymphomatous abnormalities. "Herein, we summarise the status of current research on the role and underlying mechanism(s) of GDF15 in chronic lung diseases." (PMID 37093513, 2024). "GDF15 turned out to be a general marker of cellular stress as the expression of GDF15 generally increases under pathological conditions, particularly in various chronic lung diseases; and as a key SASP factor GDF15 was linked here to senescent cell states of lung epithelial cells." (PMID 39696649, 2024). "Finally, the plasma levels of GDF15 and WFDC2 were measured due to their previous association with damage in several chronic lung diseases." (PMID 40247373, 2025). "Finally, PS patients showed increased levels of GDF15 and WFDC2, both mediators of epithelial damage, associated with lung alterations and chronic lung diseases." (PMID 40247373, 2025). "Mounting evidence suggests that GDF15, senescence, and the pathogenesis of chronic lung diseases may be interlinked." (PMID 37093513, 2024).
chronic pancreatitis (4 papers, 2020 to 2024). A chronic inflammatory process causing damage and fibrosis of the pancreatic parenchyma. "Serum GDF-15 levels in the patients with chronic pancreatitis were higher, 2248 pg/mL in mean compared to healthy subjects (416.8 pg/mL, 546, 639 in mean)." (PMID 34638326, 2021). "Pancreatic disease compressing the pancreatic duct is considered to increase the GDF-15 level, and thus can result from benign pancreatic diseases including chronic pancreatitis, intraductal papillary mucinous tumor, and serous cystic tumor." (PMID 34638326, 2021). "GDF-15 concentration in serum could be considered a biomarker in differentiating pancreatic mass due to chronic pancreatitis from pancreatic adenocarcinoma." (PMID 33201838, 2020). "Similarly, the growth differentiation factor-15 (GDF-15), a TGF-β family member, has been reported to be a robust biomarker in differentiating between chronic pancreatitis and PDAC, and this efficacy was further improved when it was analyzed in combination with MUC16." (PMID 36980526, 2023).
colon adenocarcinoma (4 papers, 2021 to 2024). "Comprehensive analysis of high throughput data has shown that GDF15 transcript is frequently expressed in various cancers, including colon adenocarcinoma." (PMID 39108882, 2024). "In colon adenocarcinoma, patients with high GDF15 had favorable overall survival, but this survival advantage was reversed when they also had decreased NK cells." (PMID 37860011, 2023). "Additionally, calcitriol decreased GDF15 expression in human colon adenocarcinoma samples, although the effect of paricalcitol was not studied." (PMID 38732029, 2024).
colorectal tumor (4 papers, 2013 to 2025). "Previous blood and colorectal tumor samples from 2 large studies also found high plasma levels of GDF15 before diagnosis of CRC are associated with greater CRC specific mortality." (PMID 39865094, 2025).
diabetic cardiomyopathy (4 papers, 2018 to 2024). Diabetic cardiomyopathy is a disorder of the heart muscle in people with diabetes. "This review explored the interplay between senescence and macrophages in diabetic cardiomyopathy, specifically focusing on the potential role of GDF-15 and Klotho." (PMID 38672115, 2024). "Additionally, the results from receiver operating characteristic curves indicated that GDF15 represents a useful and novel tool to screen for diabetic cardiomyopathy in patients with T2DM." (PMID 32222153, 2020). "Yet, in another study including 213 T2D patients without albuminuria, CKD or CVD, higher GDF-15 did predict CVD in terms of diabetic cardiomyopathy (event rate 21.1%), but adjustment did not include important risk factors such as BP, lipids, creatinine and UACR." (PMID 29698460, 2018).
diabetic neuropathy (4 papers, 2022 to 2024). A chronic, pathological complication associated with diabetes mellitus, where nerve damages are incurred due to diabetic microvascular injury involving small blood vessels that supply these nerves, resulting in peripheral and/or autonomic nerve dysfunction. "It has been shown that higher circulating levels of GDF15 are associated with progression of diabetic neuropathy." (PMID 36444166, 2022). "The findings indicate that plasma GDF-15 may be a prognostic marker for diabetic neuropathy due to its association with NIA." (PMID 39000435, 2024). "Thus, the GDF15 level is regarded as an independent risk factor for the development of diabetic neuropathy." (PMID 36444166, 2022). "Thus, the association between GDF15 and diabetic neuropathy could be a compensatory mechanism to counter‐regulate the development of microvascular dysfunction." (PMID 36444166, 2022). "The possible mechanisms by which GDF15 may be implicated in the pathogenesis of diabetic microvascular disease could involve oxidative stress, endothelial function, and immune processes, all of which are key pathogenic pathways of diabetic neuropathy." (PMID 35683420, 2022). "The present study indicates that high MMP-3 is associated with low eGFR, high plasma creatinine, and macroalbuminuria, and that GDF-15 can be a biomarker for diabetic neuropathy in T1D." (PMID 39000435, 2024). "Higher GDF15 levels in diabetic neuropathy mirror inflammatory and oxidative stress disorders, which are implicated in the pathogenesis of microvascular dysfunction and progression of diabetic neuropathy." (PMID 36444166, 2022). "Taken together, these make GDF15 to be a possible early biomarker for predicting diabetic neuropathy." (PMID 35683420, 2022). "The current study aimed to investigate the predicted role of circulating GDF15 in diabetic metabolism characteristics and diabetic neuropathy." (PMID 35683420, 2022). "In the current study, we identified a significant association between increased serum levels of GDF15 and metabolic parameters and diabetic neuropathy; thus, plasma GDF15 may be an effective independent predictor of diabetic neuropathy." (PMID 35683420, 2022). "A long-term longitudinal study may be necessary to further identify GDF15 as it is involved in diabetic neuropathy progression." (PMID 35683420, 2022). "Plasma GDF15 may be an independent predictor of diabetic neuropathy." (PMID 35683420, 2022). "The GDF15 levels were significantly elevated in patients with SSc and PNP, similarly to patients with diabetic neuropathies, were metabolic damage plays an important role." (PMID 39156689, 2024).
diabetic retinopathy (4 papers, 2020 to 2025). "In conclusion, plasma GDF-15 concentrations were positively associated with diabetic retinopathy in patients with type 2 DM." (PMID 33239667, 2020). "Our study found that plasma GDF-15 concentrations were independently and positively associated with diabetic retinopathy in individuals with type 2 DM." (PMID 33239667, 2020). "The purpose of our study was to examine the association between plasma GDF-15 concentrations and diabetic retinopathy in individuals with type 2 DM." (PMID 33239667, 2020). "Logistic regression analyses indicated that plasma GDF-15 concentrations were significantly associated with diabetic retinopathy (odds ratio per 1 standard deviation increment in the log-transformed value, 1.78; 95% confidence interval, 1.05–3.03, p = 0.032)." (PMID 33239667, 2020). "Our data indicate a close association between GDF-15 levels and diabetic retinopathy in type 2 DM patients." (PMID 33239667, 2020). "In the present study, we also found a positive association between plasma GDF-15 levels and the severity of diabetic retinopathy." (PMID 33239667, 2020). "In spite of these limitations, our data might provide a valuable information on associations between GDF-15 levels and diabetic retinopathy in patients with type 2 DM." (PMID 33239667, 2020). "Therefore, investigating whether GDF15 is implicated in the risk of diabetic retinopathy in type 2 DM patients is warranted." (PMID 33239667, 2020). "Adjusted odds ratios (ORs) of diabetic retinopathy according to quartiles of plasma growth differentiation factor 15 (GDF-15) levels." (PMID 33790859, 2021). "The AUC for GDF-15 was 0.701 (95% CI: 0.629–0.774; p < 0.001), and the optimal cut-off value was 1336 ng/L with 70.2% specificity and 64.2% sensitivity in predicting diabetic retinopathy." (PMID 33239667, 2020). "Our study showed a significant positive relationship between plasma GDF-15 concentrations and diabetic retinopathy in type 2 DM patients." (PMID 33239667, 2020). "We conducted logistic regression analysis to assess the effects of GDF-15 concentrations on diabetic retinopathy." (PMID 33239667, 2020). "Our data revealed that the severity of diabetic retinopathy might be related with plasma GDF-15 concentrations." (PMID 33239667, 2020). "In addition, in our study, multivariable analysis showed that the statistically significant relationship between GDF-15 levels and diabetic retinopathy persisted despite adjustment for confounders including hs-CRP levels." (PMID 33239667, 2020). "Consequently, the close relationship between GDF-15 and diabetic retinopathy may be explained by the common pathways involved, while the causal inferences could not be drawn in our study." (PMID 33239667, 2020). "As a consequence, our findings suggest that GDF-15 might be linked to diabetic retinopathy through mechanisms independent of CRP." (PMID 33239667, 2020). "Even though the mechanisms by which GDF-15 might be implicated in the pathogenesis of diabetic retinopathy is not clear, possible explanations have been suggested." (PMID 33239667, 2020). "In addition, our findings suggest that GDF-15 may be a valuable biomarker for discriminating diabetic retinopathy in patients with type 2 DM." (PMID 33239667, 2020). "However, the association GDF-15 levels and diabetic retinopathy in type 2 DM patients is not clear." (PMID 33239667, 2020). "Significantly increased levels of the plasma GDF-15 were found in individuals with diabetic retinopathy versus those without." (PMID 33239667, 2020). "Even though so far there are no available clinical data on the relationship between GDF-15 and pathogenesis of diabetic retinopathy in patients with type 2 DM, a possible implication of GDF-15 in progression of diabetic microvascular injury has been suggested." (PMID 33239667, 2020). "However, the relationship between plasma GDF-15 concentrations and diabetic retinopathy in type 2 DM patients is not clear." (PMID 33239667, 2020).
eating disorder (4 papers, 2024 to 2026). A broad group of psychological disorders with abnormal eating behaviors leading to physiological effects from overeating or insufficient food intake. "Present results provide novel insights into the role of GDF15 in eating disorders, describing its serum level in this clinical population for the first time." (PMID 40708105, 2026). "Nonetheless, the role of GDF15 in eating disorders (ED), which are characterised by food restriction, selective food preference, and possibly gut‐brain dysregulation, remains mostly unexplored." (PMID 40708105, 2026). "To further analyze GDF15 in relation to AN, we performed an exploratory analysis of plasma levels and eating disorder characteristics." (PMID 40562759, 2025).
emphysema (4 papers, 2017 to 2023). "For example, GDF15 exhibited a higher expression in the heat-stress group and was reported to be related to airway obstruction and emphysema parameters." (PMID 37587462, 2023). "Therefore, an examination of GDF15 was performed at the cellular level, particularly in alveolar cells, the main cells with cell membrane destruction in emphysema." (PMID 37009796, 2023). "Thus, we speculated that up-regulation of GDF15 might promote emphysema under acute heat stress." (PMID 37587462, 2023). "Again, however, GDF-15 levels were not influenced by common descriptors of COPD severity (GOLD spirometry severity, FEV1, exacerbation history) or phenotypes (chronic bronchitis, measures of emphysema or airway thickness)." (PMID 28245821, 2017).
Failure to thrive (4 papers, 2017 to 2025). Failure to thrive (FTT) refers to a child whose physical growth is substantially below the norm. "It has been demonstrated that GDF15 is required for the inhibition of liver GH signaling in failure to thrive associated with pediatric heart disease, and that children with concomitant heart disease and failure to thrive have elevated plasma GDF15." (PMID 34445593, 2021). "Plasma GDF15 is increased in children with concomitant heart disease and failure to thrive (FTT)." (PMID 28572090, 2017). "Importantly, plasma GDF15 is further increased in children with concomitant heart disease and failure to thrive (FTT)." (PMID 28572090, 2017).
glomerulonephritis (4 papers, 2020 to 2024). A renal disorder characterized by damage in the glomeruli. "We hypothesized that the mechanism underlying severe glomerulonephritis in Gdf15-/- mice could be associated with T cells." (PMID 32977372, 2020). "The significant reduction of WT-1 positive cells in aged Gdf15 knockout mice and severe models of glomerulonephritis underscores the importance of GDF15 in mitigating glomerular injury." (PMID 38607075, 2024). "Recently, a study showed that the induction of glomerulonephritis in mice can induce systemic GDF15 expression." (PMID 34669736, 2021). "Together, genes that seem to be regulated by GDF15 in the experimental mouse model of anti-GBM were induced during rapidly progressive glomerulonephritis in the glomerular and tubular compartment of the kidney." (PMID 32977372, 2020). "Here, we investigated the role of GDF15 in murine anti-glomerular basement membrane (GBM) glomerulonephritis." (PMID 32977372, 2020). "Glomerulonephritis induction in mice induced systemic expression of GDF15." (PMID 32977372, 2020). "We hypothesized that GDF15 ameliorates the anti-Glomerular Basement Membrane (GBM) glomerulonephritis by limiting the inflammation and infiltration of the immune cells into the kidney." (PMID 32977372, 2020). "This was even more pronounced in kidneys from Gdf15 knockout mice in glomerulonephritis models of anti-GBM and lupus nephritis (LN), suggesting that GDF15 may play a critical role in maintaining the integrity of the glomerular filtration barrier, podocyte survival, and glomerular inflammation." (PMID 38607075, 2024).
hyperuricemia (4 papers, 2020 to 2023). An abnormally high level of uric acid. "Associations between serum UA levels and concentrations of GDF-15 or NEFA in patients with hyperuricemia were tested using Spearman's correlation analysis." (PMID 36864452, 2023). "The current research detected that high GDF-15 concentrations were linked to high UA levels in all hyperuricemia participants, and GDF-15 levels were higher in male HUA patients suffering from CAD than in those with HUA alone, a finding that is consistent with previous work." (PMID 36864452, 2023). "42% had hyperuricemia and those had significantly higher plasma levels (p < 0.001), and uric acid was significantly correlated with plasma GDF-15 (r = 0.451, p = 0.001) and mGFR (r = ‐0.604, p < 0.001)." (PMID 32089755, 2020). "Serum circulating GDF-15 concentrations(pg/dL) [8.48(6.67,12.73)] and NEFA levels(mmol/L) [0.45(0.32,0.60)] were higher in hyperuricemia patients with CAD." (PMID 36864452, 2023). "They found that GDF-15 concentrations were correlated with uric acid, and GDF-15 levels were higher in male hyperuricemia patients suffering from CAD than in those with hyperuricemia alone." (PMID 37888100, 2023). "The current study sought to clarify the relationship between serum GDF-15/NEFA and CAD in individuals with hyperuricemia." (PMID 36864452, 2023). "Circulating GDF-15 and NEFA levels correlated positively with CAD in male patients with hyperuricemia and measurements may be a useful clinical adjunct." (PMID 36864452, 2023). "The AUC of the combined serum GDF-15 and NEFA was 0.813 (0.767,0.858) as a predictor of whether CAD occurred in male with hyperuricemia." (PMID 36864452, 2023). "Blood samples collected from 350 male patients with hyperuricemia(191 patients without CAD and 159 patients with CAD, serum UA > 420 μmol/L) to measure serum GDF-15 and NEFA concentrations with baseline parameters." (PMID 36864452, 2023).
idiopathic pulmonary arterial hypertension (4 papers, 2011 to 2022). A sporadic form of pulmonary arterial hypertension (PAH) characterized by elevated pulmonary arterial resistance leading to right heart failure. "In addition, elevated GDF-15 have been associated with higher right atrial pressures and adverse outcomes in patient with idiopathic pulmonary arterial hypertension (PAH)." (PMID 35390066, 2022). "This study evaluated different apelin isoforms in PH patients and prospectively evaluated the role of apelin-17 in comparison with NT-proBNP and GDF-15 as diagnostic marker in idiopathic pulmonary arterial hypertension (IPAH)." (PMID 36685176, 2022). "A recent study has also demonstrated elevated serum levels of GDF-15 in patients with idiopathic pulmonary arterial hypertension (IPAH)." (PMID 34920697, 2021). "In a recent study we demonstrated elevated serum levels of GDF-15 in patients with idiopathic pulmonary arterial hypertension (IPAH)." (PMID 21548946, 2011). "Growth-differentiation factor-15 (GDF-15) is a stress-responsive, transforming growth factor-β-related cytokine, which has recently been reported to be elevated in serum of patients with idiopathic pulmonary arterial hypertension (IPAH)." (PMID 21548946, 2011).
left ventricular hypertrophy (4 papers, 2012 to 2025). Enlargement of the LEFT VENTRICLE of the heart. "Rs1059519 was located at exon, which has been reported to associate with GDF-15 expression and relate to chronic hepatitis C infection, left ventricular hypertrophy." (PMID 35911685, 2022). "GDF-15 serum levels have clinical utility in patients with left ventricular hypertrophy." (PMID 33477548, 2021). "Additionally, increased plasma concentrations of suppression of tumorigenicity-2 (ST2), growth differentiation factor 15 (GDF-15), galectin-4 (Gal-4), and NT-proBNP were associated with incident HF but not consistently with left ventricular hypertrophy or diastolic dysfunction." (PMID 40141349, 2025). "ROC curves for GDF-15 were constructed for discrimination between hypertensive patients with or without left ventricular hypertrophy." (PMID 23071585, 2012).
liver failure (4 papers, 2013 to 2025). A liver disease characterized by the liver losing or has lost all of its function. "After adjusting for severity of illness, patients whose GDF-15 levels were in the third and fourth quartiles had significantly fewer cardiovascular, CNS, coagulation, renal, and hepatic failure-free days when compared to patients in the first quartile." (PMID 23706007, 2013). "Similarly, patients with GDF-15 levels in the fourth quartile had fewer cardiovascular, central nervous system (CNS), coagulation, renal, and hepatic failure-free days when compared to patients with GDF-15 levels in the first quartile." (PMID 23706007, 2013). "In conclusion, the significance of this study lies in the computational delineation of novel, intertwined circuits and common dynamic network patterns involving GDF-15, HMGB1, and MIG in the context of inflammation and liver failure." (PMID 40809145, 2024). "Potential indicators of cysteine’s influence may encompass growth differentiation factor 15 (GDF15), FGF21, blood cysteine levels, and the resolution of lactatemia and liver failure." (PMID 40430469, 2025).